MIR3158-2 (microRNA 3158-2)
Synonyms: hsa-mir-3158-2; mir-3158-2
Gene: MicroRNA gene on chromosome 10 (101,601,417 to 101,601,497, reverse strand). Ensembl gene ENSG00000283558.
Homologues: Orthologues: chimpanzee MIR3158-2 (100% identical).